NLRP3 (NLR family pyrin domain containing 3)
Diseases named in the same sentence as NLRP3 in open-access papers (continued):
Sharing a sentence is not in itself a finding about the gene and the disease.
tumor (continued). "Gene expression profiling showed that SLC31A1, LIPT2, CDKN2A, and GCSH expression was increased in tumor tissues, while NFE2L2, NLRP3, ATP7A, DLD, MTF1, and DLST expression was decreased in tumor tissues compared with normal tissues." (PMID 37065485, 2023). "NLRP3 stimulates the tumor-related MAPK signaling pathway during tumor formation and growth, promoting tumor proliferation and migration." (PMID 37715239, 2023). "However, despite the beneficial effects of NLRP3 inflammasome activation in anti-tumor vaccine therapy, the activation of NLRP3 inflammasomes by nanoparticles may also have adverse effects for cancer treatment due to the release of large quantities of pro-inflammatory cytokines (e.g., TGF-β)." (PMID 37497237, 2023). "However, this aspect of research is still controversial: some studies have shown a positive correlation between NLRP3 inflammasomes and CRC, but a part of the research holds the opposite view, they suggest that NLRP3 inflammasomes may inhibit tumor development." (PMID 37020871, 2023). "For another, the debris of tumor cells including ATP and HMGB1 act as DAMPs, triggering activating NLRP3 inflammasomes." (PMID 37817895, 2023). "The increased NLRP3 and IL1B transcripts correlated with increased biochemical caspase-1 activity in the tumor infiltrating myeloid cells compared to those isolated from PBMC from cancer patients." (PMID 36439171, 2022). "This highly inflammatory milieu modulates the immune response against tumours, while P2X7R activation, expressed on dendritic cells, play a key role in this context by activating NLRP3 inflammasome." (PMID 35267424, 2022). "Related studies also testified that NLRP3 inflammasome was increased in OSCC, and its expression was relevant to tumor stage and lymph node metastasis." (PMID 35513871, 2022). "Except for the role of CTSB on tumor cells, there are some reports that CTSB interacting with NLRP3 and to subsequent caspase-1 activation in macrophages." (PMID 36132145, 2022). "We thus analyzed the inflammatory levels in their tumor microenvironment (TME) either biologically or radiologically, focusing our attention on the NLRP3 cancer-dependent inflammasome pathway." (PMID 35884397, 2022). "From this clustering, single sample Gene Set Enrichment Analysis (ssGSEA) primarily revealed enriched IL-1 and inflammasome related pathways in NLRP3+ and INHBA+ macrophage populations in the tumor." (PMID 36439171, 2022). "To confirm that ANGPTL4 can regulate the occurrence of pyroptosis and apoptosis through the NLRP3\ASC\Caspase 8 pathway, we used tissue proteins from the xenograft tumor to re-verify the results." (PMID 36467503, 2022). "In oropharyngeal SCCs, expression of NLRP3, ASC, caspase-1, and proIL-1β/-18 is increased, suggesting a role in tumor development." (PMID 36293159, 2022). "Here, we confirm the high NLRP3 and PYCARD expression in tumor samples (50% and 31%, respectively) as well as an overexpression of CyclinD1 and MYC, (48% and 32%, respectively)." (PMID 35745570, 2022). "MEG3 knockdown suppresses the activation effect of DDP on NLRP3/caspase-1/GSDMD pathway-mediated pyroptosis and alters the inhibitory effect of DDP on tumour proliferation and metastasis in triple-negative breast cancer." (PMID 35778526, 2022). "Most genes were highly enriched in tumor tissues, while only 4 genes including ELANE, IL6, IL1B and NLRP3 were upregulated in normal tissues." (PMID 36267972, 2022). "The expression of MTF1, NLRP3, and SLC31A1 was positively related with ImmuneScore, StromalScore, and ESTIMATEScore in almost all types of tumor, whereas ATP7B, DLAT, DLD, LIAS, PDHA1, and PDHB were significantly negatively correlated with the scores." (PMID 36387247, 2022). "Inflammatory cytokines such as IL-1β, TNFα, and IFNγ are produced to combat the initial tumor via activation of NF-κB, STAT1, and NLRP3 inflammasome pathways." (PMID 36555392, 2022).
tumor (continued). "It is reported that the NLRP3/caspase-1/GSDMD-dependent pyroptosis is enhanced in NSCLC cells treated with polyphyllin VI, leading to the elimination of tumor cells." (PMID 35819638, 2022). "Notably, our clinical findings were supported by data from the gp130F/F preclinical GC model, in which NLRP3 deficiency had no impact on tumor burden or well-documented tumor-promoting cellular processes, namely, cell proliferation and survival, inflammation, and angiogenesis." (PMID 35299732, 2022). "We noted differentially increased inflammasome complex transcripts, including NLRP3 and IL1B genes in the tumor-infiltrating myeloid cells compared to those in circulation." (PMID 36439171, 2022). "On the contrary, NLRP3 in colorectal cancer (CRC) inhibits tumor growth, senses tissue damage, and activates cell death mechanisms against the tumor cells." (PMID 35205167, 2022). "The second study also revealed high expression of NLRP3 in cell lines and paraffin-embedded human oral SCC tissues, with a good correlation between NLRP3 expression levels, tumour size, and lymph node metastatic status." (PMID 36325196, 2022). "Ech upregulated the expression of NLRP3 and caspase-1 in nude mice NSCLC transplant tumor tissues and inhibited the growth of nude mice NSCLC transplant tumors." (PMID 35571569, 2022). "NLRP3 knockdown inhibits the proliferation, migration, and invasion of oral SCC cells and reduces tumour growth in vivo." (PMID 36325196, 2022). "In summary, our study provides novel insights into the NLRP3 inflammasome downstream signaling in combination with CCD1 activation and alterations in BC patients and in particular in the Luminal tumor phenotype." (PMID 35745570, 2022). "The NLRP3 inflammasome, acting as a scavenging and effector system in the HCC TME, significantly shapes the anti-tumor immune response." (PMID 35804922, 2022). "The P2X7R-induced activation of NLRP3 also leads to IL-1β production and subsequent stimulation of CD4+ and CD8+ T lymphocytes, which mediate anti-tumour responses." (PMID 35267424, 2022). "Among these DEGs, 5 genes were down-regulated in tumor group including IL1B, AIM2, IL6, NLRP3, and NLRP6." (PMID 36127654, 2022). "Immunohistochemistry (IHC) was used to evaluate the differential expression of major PRGs (GSDMC, GSDMD, GSDME, NLRP3, NLRC4, IL1B) in selected tumor types (COAD, HNSC, KIRC, LIHC, LUAD, LUSC)." (PMID 36605187, 2022). "Our recent data demonstrated a higher NLRP3 and PYCARD expression in the tumor compartment with respect to the non-tumor areas in a BC cohort." (PMID 35745570, 2022). "Preclinical evaluation has demonstrated that NLRP3 inflammasome mediated IL-1β and IL-18 release results in IFN-γ production and CD8+ T cell-dependent tumor regression." (PMID 33572196, 2021). "Macrophage-specific deletion of Glucose Transporter 1 (GLUT1) significantly reduced tumor burden, which was accompanied by increased Natural Killer and CD8+ T cell activity and suppression of the NLRP3-IL1β inflammasome axis." (PMID 34198548, 2021). "Our previous study has shown that while nigericin induced tumor cell death, inhibitors of NLRP3, including VX765 and glibenclamide, promote tumor cell proliferation." (PMID 34577552, 2021). "Since the proinflammatory environment is known to support tumor cell proliferation and survival, but excessive inflammation can also lead to cell death, unrestricted inflammasome activation might be prevented by the induction of mitophagy in order to dampen NLRP3 inflammasome activation." (PMID 33525345, 2021). "Conversely, tumor-derived exosomal TRIM59 has been shown to rewire macrophages towards a protumoral pathway by degrading ABHD5 protein and exacerbating NLRP3 inflammasome activation, which promotes LC cell proliferation and invasion." (PMID 34064909, 2021).
tumor (continued). "After constructing a tumor-bearing mice model, galloflavin was intragastrically administered, followed by detection of tumor growth, expression of NLRP3 and ASC by immunohistochemistry, and tumor histopathology by H&E staining." (PMID 34955826, 2021). "At the same time, the anti-tumor effect of PG on HOS and SAOS-2 cells is mediated by the NLRP3 inflammasome activated by endoplasmic reticulum stress." (PMID 34381721, 2021). "Knockdown of MEG3 abolished the activation effect of DDP on NLRP3/caspase-1/GSDMD pathway-mediated pyroptosis, and reversed the suppression of DDP on tumor growth and metastasis ability in vitro and in vivo." (PMID 34326697, 2021). "Mechanistically, activation of P2RX7 leads to increased production of IL-18 in a NLRP3-dependent manner, which in turn activates NK and CD4+ T cells to produce IFN-γ and consequently increases tumor immunogenicity." (PMID 33510147, 2021). "Taken together, these data suggested that DDP-induced pyroptosis suppressed tumor growth and metastasis via MEG3/NLRP3/caspase-1/GSDMD pathway in a xenograft animal model." (PMID 34326697, 2021). "Mice with PTEN-deficient myeloid cells exhibit decreased chemotherapy-induced NLRP3 activity in the tumour microenvironment and resistance to Mitoxantrone, suggesting that PTEN-induced NLRP3 activity promotes anti-tumour immunity and tumour suppression." (PMID 34854899, 2021). "DC activation by binding to ATP also promotes caspase-1 dependent NLRP3 inflammasome formation and the release of IL-1β, which in turn promotes CD8+ T cells and IL-17 producing-γδ T cell mediated anti-tumor response." (PMID 34263254, 2021). "Either genetic or pharmacological inhibition of tumor-derived NLRP3 by dapansutrile (OLT1177) was sufficient to reduce MDSCs expansion and to enhance antitumor immunity, resulting in reduced tumor growth." (PMID 33649199, 2021). "ADAMTS9-AS2 functions as a tumor suppressive lncRNA and sensitizes GC cells to CDDP by inducing NLRP3-mediated pyroptotic cell death via downregulating miR-223-3p." (PMID 34805143, 2021). "In anti-PD-1 treated solid tumor murine models, activated CD8+ T cells induced NLRP3 inflammasome activation within tumor cells, which resulted in downstream Wnt5a-mediated CXCR2 ligand expression and MDSC recruitment into the tumor tissue." (PMID 33572196, 2021). "Pharmacological inhibition of NLRP3 with MCC950 significantly inhibits platelet activation and aggregation and tumor progression." (PMID 34064909, 2021). "The expression of pyroptosis-related proteins such as gasdermin family, caspase family, NLRP3, ASC, etc. are mostly different between tumor tissues and normal tissues." (PMID 34381721, 2021). "Linking tumor-NLRP3 induction of IL-6/STAT3 to immunosuppression, we assessed PMN-MDSCs in bone marrow and spleen from tumor-bearing mice treated with OLT1177." (PMID 34531850, 2021). "High NLRP3, PYCARD and TLR4 expression was found in 31.8% (106/333), 38.6% (129/334) and 35.6% (115/323) of the tumor samples, respectively." (PMID 34540671, 2021). "The expression of P2X7R is controlled by NLRP3, such that the downmodulation of NLRP3 drives P2X7R expression and simultaneously contributes to tumor growth, whereas NLRP3 overexpression inhibits cell proliferation and induces cell death." (PMID 33525345, 2021). "Upregulation of the NLRP3 inflammasome in OSCC cells was reported to correlate positively with IL-1β expression level, tumour growth, and lymph node metastatic status." (PMID 33918087, 2021). "This study showed NLRP3 in CAFs to mediate IL-1β-dependent recruitment of both CD11b+Ly6CloLy6G+ PMN-MDSCs and CD11b+Ly6ChiLy6G− monocytic MDSCs into the tumor bed depending on the genetic background of the tumor model." (PMID 34638239, 2021). "In conclusion, in this study, we, for the first time, analyzed the effect of an inducer (Nigericin) of NLRP3 and inhibitor of Caspase 1 (VX765) in a panel of different tumor types and normal fibroblast controls." (PMID 33613529, 2020).
tumor (continued). "Through IHC experiments, we found that CD44s, NLRP3, caspase-1, and IL1B were expressed in most tumor cells, and we demonstrated the positive relationship between CD44s and caspase-1 by quantifying IHC results." (PMID 33168816, 2020). "We propose that the differences in the level of NLRP3 activation in tumor cell lines are related to variations in the inflammatory nature of the individual tumor types, where pro-inflammatory cytokines produced by the tumor could act as priming agents, instead of LPS." (PMID 33613529, 2020). "Though tumor tissue sections in the HRW and NC groups presented moderate-to-strong positive expression of NLRP3, caspase-1 and GSDMD, the HRW group showed much higher staining by IHC." (PMID 31924176, 2020). "Downstream of RLR family members, expression of NLRP3 inflammasome components are impaired in HCC tumor tissues, i.e., ASC, caspase 1 and IL-1β, which inversely correlated with tumor grade and clinical stage." (PMID 33613561, 2020). "Because an increased expression of NLRP3, ASC, Caspase-1, IL-1β and IL-18 proteins is observed in tumor tissues from Tgfbr1/Pten 2cKO HNSCC mice, there is a rationale for testing the NLRP3 inflammasome inhibitor, MCC950 in this model." (PMID 33261061, 2020). "In sarcoma and metastatic melanoma models, NLRP3 activation enhances MDSC and Treg populations while suppressing both NK and T cell-mediated tumor surveillance." (PMID 33613533, 2020). "This study found that TAM NLRP3 expression was controlled by TGF-β in vivo, a known secretion product of tumour cells." (PMID 32883606, 2020). "We first assessed the immunofluorescence intensity of selected inflammasome components (NLRP1, NLRP3, NLRP6, AIM2, ASC, Caspase-1, IL-1β and IL-18) in tumor cells compared to normal epithelial cells, for each patient." (PMID 33255437, 2020). "This study highlighted the capacity of PD-L1 to drive immunosuppression, through NLRP3 activation in tumor cells, MDSC recruitment and CD8+ T cells inhibition, without exploring the effects of therapy combining anti-PD-L1 with NLRP3/caspase-1 inhibitor." (PMID 33261061, 2020). "We demonstrated that highly purified DHA enhances 5-FU anti-tumor efficacy in a murine cancer model, by repressing 5-FU-induced IL-1β secretion in MDSC under the control of NLRP3 inflammasome and JNK pathway through β-arrestin-2." (PMID 31217433, 2019). "Anthracyclines induce ICD, resulting in exposure of calreticulin on the surface of tumor cells, tumor secretion of high mobility group box 1 and activation of NLR Family Pyrin Domain Containing 3 (NLRP3) inflammasome in DC." (PMID 30979057, 2019). "Therefore, we speculate that NLRP3 is involved in tumor aggressiveness." (PMID 31312615, 2019). "It appears that NLRP3 promotes OSCC growth and tumor spread, which makes miR-22 a potential therapeutic target for cancer treatment." (PMID 31118894, 2019). "By specifically targeting the expression of NLRP3 and IL-1β in mammary fibroblasts, we showed in multiple mouse models that CAF-derived inflammasome is functionally important for facilitating tumour growth." (PMID 31558756, 2019). "miR-223 regulates several targets, such as NLRP3, NFIA, and PARP1, that are involved in the induction of apoptotic mechanisms observed in AYA-RMS tumor tissues." (PMID 31533233, 2019). "Via activation of NLRP3 inflammasome, PC3-derived EVs are likely to contribute to the auto-perpetuating inflammatory loop, a tumour characteristic." (PMID 31480312, 2019). "Several genes encoding core inflammasome components were all significantly expressed at higher levels in ACP tumours compared with control tissues, including NLRP1 (6.4-fold), NLRP3 (4.8-fold), NLRC4 (4.8-fold), CASP1 (5-fold) and PYCARD (4-fold) [Suppl." (PMID 29541918, 2018). "We found that NLRP3 was aberrantly overexpressed in OSCC cells, and the abnormal expression was correlated with the tumor stage, lymph node metastatic status and IL-1β expression level." (PMID 29716544, 2018).
tumor (continued). "Similar to tumour antigen-specific CTL-mediated antitumour immunity, we found that MLR antigen-specific CTLs activated NLRP3 inflammasome for IL-1β production in APCs, and the CTL-mediated GVHD induced IL-1β production through NLRP3 inflammasome." (PMID 28537251, 2017). "It is possible that components from dying tumor cells such as ATP, HMGB1, or oxidized DNA induce the activation of NLRP3 inflammasome." (PMID 27786298, 2016). "The work from the same lab stated that 5-FU also induces activation of NLRP3 in dying MDSC, leading to secretion of IL-1β, elicitation of TH17 cells, IL-17 production and tumor growth following increased angiogenesis." (PMID 27645787, 2016). "Therefore, we investigated whether NLRP3 contributes to tumor growth and metastasis." (PMID 27786298, 2016). "Here, we show that the NLRP3 inflammasome-related proteins, ASC, IL-1β, CASP1, and NLRP3, are all highly expressed in OSCC tumor cells compared to adjacent normal cells." (PMID 27367024, 2016). "In sum, these results obtained from the TCGA database indicate that across tumor stages, NLRP1, NLRP3, NLRC3, NLRC4 and AIM2 expression in CRC tissues was significantly less than healthy controls." (PMID 26378020, 2015). "In NPC, NLRP3, AIM2 and RIG-I inflammasomes were overexpressed in the tumour cells and were required for IL-1β production in response to PAMPs and DAMPs in the tumour microenvironment and therapeutic treatment." (PMID 23065753, 2012). "Experimental inhibition of NLRP3 or caspase-1 has been shown to suppress OSCC cell migration, invasion, and proliferation, underscoring the contribution of NLRP3 inflammasome signaling to tumor progression." (PMID 41596738, 2026). "Consequently, NLRP3-induced cytokines accelerate angiogenesis, mediate immune suppression, promote EMT, and foster a tumor-permissive microenvironment that advances OSCC progression." (PMID 41596738, 2026). "In accordance, upon using an NLRP3 inhibitor, BAY117082, the NLRP3 inflammasome components expression and activation were inhibited, resulting in the reduction in OSCC cell viability in vitro and a reduction in tumour mass in vivo mouse models." (PMID 41440367, 2025). "Activation of NLRP3, TLR3 and TLR4 may lead to chronic inflammation, which contributed to immune evasion and tumor progression." (PMID 40535567, 2025). "On one hand, inflammasomes such as NLRP3 and AIM2 can suppress tumorigenesis by enhancing anti-tumor immunity through the activation of caspase-1 and subsequent maturation and release of pro-inflammatory cytokines like IL-1β and IL-18, which recruit and activate immune cells." (PMID 40692785, 2025). "Recent evidence links NLRP3 signaling to granulocytic recruitment in the TME and therapy antagonism, further supporting that inflammasome and tumor-promoting inflammation modulation may have strong antiglioma action." (PMID 41463173, 2025). "Nevertheless, both the chemo > STING/α-PD-1 + α-CTLA-4 and the chemo > NLRP3/α-PD-1 + α-CTLA-4 groups showed slower tumor growth than the chemo > α-PD-1 + α-CTLA-4 group, respectively, especially the NLRP3 agonist-based combination therapy, which reached statistical significance." (PMID 39871312, 2025). "Furthermore, a Western blot assay was used to analyze tumor samples, which showed elevated levels of TLR4 and p-p65 in the 216911KO tumors, indicating the activation of the TLR4/NFκB/NLRP3 signaling pathway." (PMID 39824843, 2025). "IL-6 enhances immune cell recruitment and promotes tumor progression by inducing epithelial-to-mesenchymal transition (EMT) and angiogenesis, while IL-1β and IL-18 are key pro-inflammatory cytokines activated by the NLRP3 inflammasome pathway." (PMID 40218944, 2025). "In addition, NLRP3 expression was significantly positively correlated with infiltrating levels of all immune cell types that influence the TME and regulate tumor behavior." (PMID 41560727, 2025).